MAK16 (MAK16 homolog)
Synonyms: RBM13; MAK16L
Tractability: Small molecule: a structure with a bound ligand is known. PROTAC: UniProt records ubiquitination sites on it; ubiquitination databases record sites on it; its protein half-life has been measured.
Gene: Protein-coding gene on chromosome 8 (33,484,696 to 33,501,262, forward strand). Ensembl gene ENSG00000198042.
Subcellular location: Nucleus, nucleolus
Subcellular location (Human Protein Atlas): Nucleoli; Vesicles
Gene Ontology:
Molecular function: protein binding; RNA binding
Biological process: maturation of 5.8S rRNA; maturation of LSU-rRNA
Cellular component: nucleolus; preribosome, large subunit precursor
Genetic constraint (gnomAD): Loss-of-function variants: 8 observed, 43.72 expected, observed/expected ratio (o/e) 0.18, 90% interval 0.11 to 0.33. The upper end of that interval is the gene's LOEUF score, 0.33, which puts it in group 1 of 6, group 1 being the genes least tolerant of losing a copy. Missense variants: 255 observed, 339.46 expected, observed/expected ratio (o/e) 0.75, 90% interval 0.68 to 0.83. Synonymous variants: 102 observed, 120.65 expected, observed/expected ratio (o/e) 0.85, 90% interval 0.72 to 1.
Homologues: Orthologues: chimpanzee MAK16 (99% identical), macaque MAK16 (98% identical), pig MAK16 (94% identical), rabbit MAK16 (94% identical), dog MAK16 (93% identical), mouse Mak16 (89% identical), rat Mak16 (86% identical), tropical clawed frog mak16 (79% identical), zebrafish mak16 (74% identical), Caenorhabditis elegans C16A3.6 (52% identical), Drosophila melanogaster Rbm13 (52% identical).
Diseases named in the same sentence as MAK16 in open-access papers:
MAK16 is named in the same sentence as 5 diseases in open-access papers, as found by Europe PMC text mining. Sharing a sentence is not in itself a finding about the gene and the disease. The quoted sentences say what the papers report.
viral infection (2 papers, 2023). "The role of MAK16 and H3Y2 in viral infection is unclear, while RBMX, which encodes X-ed RNA binding motif proteins, responds to SARS-CoV-2 entry via viral RNA-host protein interactions." (PMID 36690780, 2023).
sleeping sickness (1 paper, 2025). "In T. brucei, the causative agent of African trypanosomiasis (sleeping sickness), Mak16 thus appears to be an important client of both the ISC and CIA machineries, highlighting the essential role of Fe/S cluster biogenesis in this pathogen (40, –42)." (PMID 41231949, 2025).
tumours (1 paper, 2020). "At present, there is still no study of the role of MAK16 in the pathogenesis of tumours, which requires further research to confirm." (PMID 32828126, 2020).
MAK16 also shares sentences with these, for which no sentence is quoted: cancer (1 paper); migraine (1).